DNAAF3 (dynein axonemal assembly factor 3)
Description:
Required for the assembly of axonemal inner and outer dynein arms. Involved in preassembly of dyneins into complexes before their transport into cilia.
Synonyms: C19orf51; FLJ40069; FLJ36139; pf22; PCD; CILD2; DAB1
Tractability: Antibody: its Gene Ontology location is reachable by antibodies, with medium confidence. PROTAC: ubiquitination databases record sites on it.
Gene: Protein-coding gene on chromosome 19 (55,158,661 to 55,166,722, reverse strand). Ensembl gene ENSG00000167646.
Subcellular location: Cytoplasm; Dynein axonemal particle
Subcellular location (Human Protein Atlas): Cytosol; Vesicles
Gene Ontology:
Biological process: axonemal dynein complex assembly; motile cilium assembly
Cellular component: dynein axonemal particle; cytoplasm
Genetic constraint (gnomAD): Loss-of-function variants: 38 observed, 43.72 expected, observed/expected ratio (o/e) 0.87, 90% interval 0.67 to 1.14. The upper end of that interval is the gene's LOEUF score, 1.14, which puts it in group 4 of 6, group 1 being the genes least tolerant of losing a copy. Missense variants: 760 observed, 701.43 expected, observed/expected ratio (o/e) 1.08, 90% interval 1.02 to 1.15. Synonymous variants: 326 observed, 299.91 expected, observed/expected ratio (o/e) 1.09, 90% interval 0.99 to 1.19.
Gene-disease validity (ClinGen):
ClinGen rates the evidence that DNAAF3 causes each of these diseases.
primary ciliary dyskinesia 2 (autosomal recessive): Definitive.
Homologues: Orthologues: macaque DNAAF3 (93% identical), chimpanzee DNAAF3 (85% identical), pig DNAAF3 (77% identical), dog DNAAF3 (74% identical), rat Dnaaf3 (73% identical), mouse Dnaaf3 (72% identical), guinea pig DNAAF3 (66% identical), tropical clawed frog dnaaf3 (36% identical), zebrafish dnaaf3l (31% identical), zebrafish dnaaf3 (30% identical), Drosophila melanogaster Dnaaf3 (26% identical). Paralogues in human: CRACDL (14% identical).
Diseases named in the same sentence as DNAAF3 in open-access papers:
DNAAF3 is named in the same sentence as 21 diseases in open-access papers, as found by Europe PMC text mining. Sharing a sentence is not in itself a finding about the gene and the disease. The quoted sentences say what the papers report.
Infertility (5 papers, 2021 to 2025). "In this study, we identified a new DNAAF3 mutation through the genetic analysis of an infertile male in China and attempted to generate a corresponding mouse model, which suggests the relevance of DNAAF3 in the pathogenesis of PCD." (PMID 39289782, 2024). "Additionally, the study reported the first case of infertility associated with a DNAAF3 mutation, in which the patient was diagnosed with immotile sperm; however, more detailed semen analysis results were not provided." (PMID 39289782, 2024). "However, there are very few reports on PCD in infertile males with DNAAF3 mutations and on their semen characteristics, with only two cases reported thus far." (PMID 39289782, 2024). "Here, we identified a novel mutation in DNAAF3 from an infertile and PCD patient with severe asthenozoospermia and revealed that the deleterious mutation of DNAAF3 may be the key factor responsible for infertility." (PMID 37537752, 2023). "Among women with known genetic results, those with infertility had DNAH5, DNAAF3, ZMYND10, CCDC40, RSPH9 and HYDIN mutations." (PMID 40142748, 2025). "In summary, research on the association between DNAAF3‐ and PCD‐related infertility remains limited among the reported DNAAF family gene mutations." (PMID 39289782, 2024). "We identified a novel biallelic mutation in DNAAF3 gene (c.551T>A; p.V184E) in a PCD patient with infertility with severe asthenozoospermia." (PMID 37537752, 2023). "In this study, we identified a novel biallelic mutation in the DNAAF3 gene (c.551T>A; p.V184E) in a PCD patient with infertility due to severe asthenozoospermia." (PMID 37537752, 2023). "To date, only two cases of PCD with infertility associated with DNAAF3 mutations have been reported, and no mouse models for this gene have been successfully constructed." (PMID 39289782, 2024). "Importantly, Dnaaf3ΔCR infertility could be substantially rescued by the Dnaaf3-mVenus fusion gene." (PMID 34553759, 2021).
male infertility (4 papers, 2020 to 2024). The inability of the male to effect fertilization of an ovum after a specified period of unprotected intercourse. "Despite the limitations, the findings of this study provide new insights into the relationship between DNAAF3 mutations and male infertility associated with PCD." (PMID 39289782, 2024). "This study expands the spectrum of DNAAF3 mutations and supplements the pool of male infertility cases attributed to DNAAF3 mutations." (PMID 39289782, 2024). "The results of this study expand the spectrum of DNAAF3 mutations and provide important clues for investigating the mechanisms underlying DNAAF3‐related male infertility associated with PCD." (PMID 39289782, 2024). "Five other dynein preassembly genes (DNAAF1, DNAAF3, DNAAF5, SPAG1, and CFAP298 (C21orf59)) are known to be associated with PCD and putatively, male infertility." (PMID 33635866, 2021). "A previous study found a case of male infertility due to immobility sperm in PCD patient with DNAAF3 mutations, but did not investigate the fertility status of other PCD patients." (PMID 37537752, 2023). "In addition to mutations in DNAAF2, PCD-causing mutations in DNAAF1, DNAAF3 and DNAAF4 have been reported to cause male infertility, but the patient number is minimal." (PMID 31781811, 2020).
primary ciliary dyskinesia (4 papers, 2019 to 2023). A rare, genetically heterogeneous, primarily respiratory disorder characterized by chronic upper and lower respiratory tract disease. "A previous study identified a high mutation rate of DNAAF3 in patients with primary ciliary dyskinesia." (PMID 37711621, 2023). "Dynein axonemal assembly factor 3 (Dnaaf3) is one of the dynein assembly factors associated with primary ciliary dyskinesia." (PMID 37935354, 2023). "Mutations in DNAAF3 cause defects in the cytoplasmic preassembly of the dynein arms and are associated with the phenotype primary ciliary dyskinesia with an autosomal recessive inheritance pattern." (PMID 36003331, 2022). "Additionally, DNAAF3 has been reported to be associated with primary ciliary dyskinesia." (PMID 37711621, 2023).
asthma (3 papers, 2022 to 2024). "Additional genetic factors, such as genetic variations in some PCD-causing genes (DNAH14, DNAAF3, DNAH6, DNAH5, KIFC2, KIF3A), are associated with the increased risk of asthma development." (PMID 39337527, 2024).
asthenozoospermia (2 papers, 2023 to 2024). "Pedigree analysis showed that PCD with severe asthenozoospermia caused by DNAAF3 mutation is an autosomal‐recessive mode of inheritance." (PMID 37537752, 2023). "Based on these results, we hypothesized that the homozygous mutation in DNAAF3 was associated with PCD combined with severe asthenozoospermia." (PMID 37537752, 2023). "When DNAAF3 gene mutations cause structural abnormalities, the outer and inner dynein arms may be absent at the ultrastructural level, resulting in immotile sperm or severe asthenozoospermia, thus affecting male reproductive potential." (PMID 39289782, 2024). "In this study, we identified a novel DNAAF3 mutation in a Chinese male suffering with PCD and severe asthenozoospermia." (PMID 39289782, 2024). "Based on these results and the following DNAAF3 gene mutation validation, PCD along with asthenozoospermia was diagnosed." (PMID 37537752, 2023). "In this study, we identified a novel mutation in the DNAAF3 gene through WES of samples from an infertile Chinese male; bioinformatics analysis showed that this variant was highly pathogenic, and may have led to PCD‐related phenotypes, such as bronchitis and severe asthenozoospermia, in this male." (PMID 39289782, 2024).
bronchiectasis (2 papers, 2023 to 2024). Segmental, irreversible dilation of the bronchial tree resulting in the accumulation of secretions which leads to obstruction. "DNAAF3 is identified as a novel gene associated with PCD and different mutations in DNAAF3 results in different clinical features of PCD patients, such as situs inversus, sinusitis and bronchiectasis." (PMID 37537752, 2023).
cystic fibrosis (1 paper, 2024). Autosomal recessive disorder caused by pathogenic variants in the CFTR gene (cystic fibrosis transmembrane conductance regulator), which encodes a chloride and bicarbonate channel expressed in epithelial cells, and follow the diagnosis criteria. "Variants in genes underlying the development or function of cilia, such as DNAH14 and DNAAF3, were associated with poor lung function in cystic fibrosis, whereas variants in DNAH6 were associated with preserved lung function in cystic fibrosis." (PMID 39337527, 2024).
gastric cancer (1 paper, 2023). A primary or metastatic malignant neoplasm involving the stomach. "We also demonstrated that the knockdown of DNAAF3 can reduce gastric cancer migration and proliferation and decrease the activation of T cell caused by gastric cancer in tumor microenvironment." (PMID 37711621, 2023). "In our current investigation, we observed that gastric cancer cells with DNAAF3 gene knockdown exhibited reduced transwell membrane crossing ability and colony formation capacity." (PMID 37711621, 2023). "In order to investigate the mechanism by which DNAAF3 in gastric cancer cells affects T cells, the relevant marker was assessed using RT-qPCR." (PMID 37711621, 2023). "Our study presents evidence suggesting that DNAAF3 may play a positive regulatory role in the activation of Treg cells induced by gastric cancer through the β-Catenin-induced CCL28 pathway." (PMID 37711621, 2023). "Moreover, the activation of T cell that co-cultured with gastric cancer cell was reduced after DNAAF3 gene knockdown in cancer cells." (PMID 37711621, 2023). "Specifically, DNAAF3 has been verified maybe an oncogene in gastric cancer, exerting an influence on both migration and proliferation capabilities." (PMID 37711621, 2023). "Suppression of DNAAF3 has been observed to diminish the migratory and proliferative capabilities of gastric cancer, as well as attenuate the activation of T cells induced by gastric cancer within the tumor microenvironment." (PMID 37711621, 2023). "However, there is currently no research available on the association between DNAAF3 and gastric cancer or T cell." (PMID 37711621, 2023). "The results demonstrated that the knockdown of DNAAF3 led to a decrease in the expression of β-Catenin and its downstream target CCL28 in gastric cancer, resulting in the suppression of Treg cell (FOXP3+) infiltration." (PMID 37711621, 2023).
gastric tumor (1 paper, 2023). "The results obtained from reverse transcription-quantitative polymerase chain reaction (RT-qPCR) and immunohistochemical indicated that the expression levels of CGB5, UPK1B, and PI15 were downregulated in gastric tumor cells, while DNAAF3 was upregulated." (PMID 37711621, 2023).
tumor (1 paper, 2023). "From the RT-qPCR and immunohistochemical, the expression of DNAAF3 was higher in tumor and the expression of PI15, UPK1B, and CGB5 was lower in tumor." (PMID 37711621, 2023). "Additionally, the investigation of the expression of four signature genes in the tumor immune microenvironment through single-cell sequencing analysis confirmed the presence of CGB5, PI15, UPK1B, and DNAAF3 in the T cell cluster." (PMID 37711621, 2023).
DNAAF3 also shares sentences with these, for which no sentence is quoted: lung disease (2 papers); sinusitis (2); situs inversus (2); bronchitis (1); cancer (1); ciliopathies (1); Cough (1); Hydrocephalus (1); Kidney Cyst (1); lower respiratory tract infections (1); teratospermia (1).